RNU6-1191P (RNA, U6 small nuclear 1191, pseudogene)
Gene: Small nuclear RNA gene on chromosome 16 (81,106,533 to 81,106,639, reverse strand). Ensembl gene ENSG00000252608.
Homologues: Orthologues: mouse Gm25522 (54% identical). Paralogues in human: RNU6-854P (73% identical), RNU6-517P (71% identical), RNU6-73P (70% identical), RNU6-946P (70% identical), RNU6-1011P (69% identical), RNU6-1124P (69% identical), RNU6-1277P (69% identical), RNU6-166P (69% identical), RNU6-266P (69% identical), RNU6-330P (69% identical), RNU6-338P (69% identical), RNU6-514P (69% identical), and 1286 more.